CTLA4 (cytotoxic T-lymphocyte associated protein 4)
Diseases named in the same sentence as CTLA4 in open-access papers (continued):
Sharing a sentence is not in itself a finding about the gene and the disease.
colitis (continued). "Writing recently in Science, Lo and coworkers characterized a critical role of the gut microbiota in CTLA‐4 blockade‐induced colitis, revealing that an Fc domain‐deficient anti‐CTLA‐4 antibody can elicit antitumor responses effectively while avoiding the induction of colitis‐like disease." (PMID 38881673, 2024). "Key clinical features, colitis scores and accumulation of CD11b+ Gr-1high neutrophils were more severe in recipients of anti-CTLA4 and anti-PD-1 combination treatment than single agent treatment, and changes in anti-PD-1 recipients were generally milder than in anti-CTLA4 monotherapy." (PMID 37872166, 2023). "While combination anti-PD-1 and anti-CTLA-4 therapy has been shown to be clinically effective against various tumor types, the high incidence of developing immune-related adverse events, such as colitis, limits widespread use, particularly in older patients with multiple medical comorbidities." (PMID 36867675, 2023). "In addition, antibiotic-mediated bacterial clearance may aggravate unexpected adverse reactions; for example, vancomycin and anti-ctla-4 can lead to more severe and fatal colonic inflammation in mice with colitis." (PMID 35749000, 2022). "correlated with smaller tumor sizes, whereas reconstitution with Bacteroides fragilis and Burkholderia cepacia reduced colitis like histopathological changes from anti-CTLA-4, hypothesizing that Bacteroides fragilis elicits an IL-12-dependent TH1 immune response." (PMID 35474500, 2022). "Interestingly, histology differs between anti-CTLA-4 and anti-PD-1 induced colitis." (PMID 34221257, 2021). "However, the increased expression of CTLA4 was observed only in CD4+Foxp3+ T cells in colitis." (PMID 34336843, 2021). "Moreover, a high-level infiltration of CD4+ T cells and CD8+ T cells was reported in patients with severe colitis following immunotherapy, of which the former was more prevalent in those who underwent anti-CTLA-4 therapy and the latter usually occurred in anti-PD-1-induced colitis." (PMID 34992611, 2021). "Also, up to 1/3 of patients on CTLA-4 therapy develop colitis." (PMID 32944086, 2020). "In another prospective analysis of 26 anti-CTLA-4 treated patients using 16S rRNA sequencing, a significantly lower abundance of Bacteroidetes but higher abundance of Firmicutes at baseline was reported in the nine patients who developed ICI-associated colitis." (PMID 33643899, 2020). "In addition, the frequency of CD4+ICOS+ T cells was also shown to be unexpectedly elevated in non-tumor tissues during treatment with CTLA-4 antibody, causing immune-related adverse events, such as colitis, which should be improved in the future." (PMID 32983168, 2020). "Thus, the data from our B16 tumor model and DSS-induced colitis are consistent with clinical observations in patients who received ipilimumab (anti-CTLA-4 antibody), and/or nivolumab (anti-PD-1 antibody), for whom colitis is the most commonly encountered problem." (PMID 31214189, 2019). "Indeed, novel evidence supports the idea that in both anti-CTLA-4 and anti-PD-1 colitis, specific “favorable” or “unfavorable” microbiome profiles may affect the efficacy of the immune response and, consequently, the appearance of gastrointestinal irAEs." (PMID 31214189, 2019). "In a study conducted by researchers, mouse models of colon cancer and melanoma were generated, and colitis was induced using low-dose DSS and ICIs with anti-CTLA4 and anti-PD1." (PMID 39456702, 2024). "This interplay, when activated by anti-CTLA4 and anti-PD1/PD-L1, contributes to the genesis of a microenvironment within the intestines that is highly conducive to the onset of ICI colitis." (PMID 38339367, 2024). "Following first-line therapy with corticosteroids, CTLA4 inhibitor–induced colitis recurs in about 44% of patients, and PD1/PDL1 inhibitor–induced colitis recurs in about 34% of patients." (PMID 39311981, 2024).
colitis (continued). "Regarding serious colitis, we found that ICI combination was the worst-ranked treatment modality and anti-CTLA-4 agents were the second-worst ranked treatment modality." (PMID 38372756, 2024). "The combination of ICIs significantly elevated the incidence of colitis and hypothyroidism compared to the use of PD1/PD-L1 inhibitors or CTLA4 inhibitors alone." (PMID 38611115, 2024). "An activated effector population of ICOS+ cells was relatively enriched amongst infiltrating CD4+ T-cells in biopsies from both anti-CTLA-4 and anti-PD1-induced colitis compared with those from IBD patients." (PMID 36776862, 2023). "Higher rates have been reported in patients treated with anti-CTLA4 antibodies compared to anti-PD1 for both diarrhea and colitis (30.2–35.4% vs. 12.1–13.7% and 5.7–9.1% vs. 0.7–1.6%, respectively)." (PMID 35631383, 2022). "Out of 58 MM patients treated with anti-PD-1 or anti-CTLA-4 ICI, 20 irAE of interest (colitis, pneumonitis, and thyroiditis) were observed on 18F-FDG PET/CT scans in 18 (31%) patients: the bowel N=6 (11%), lung N=5 (9%), and thyroid N=9 (16%)." (PMID 34958422, 2022). "Improvement in colitis was found to be IL-10, TGF-β, and CTLA-4 dependent after administration of antagonistic IL-10 receptor, TGF-β, and CTLA-4 antibodies." (PMID 36466912, 2022). "Researchers established an ICI-related colitis mice model by combining dextran sulfate sodium (DSS) and anti-CTLA-4 to simulate the inflammation condition." (PMID 36389768, 2022). "In patients with metastatic melanoma that were given ICI therapy that included anti–CTLA-4, an increased number if IL-17A–secreting CD4 T-cells (TH17) was observed in peripheral circulation of those who developed colitis." (PMID 35047501, 2021). "Moreover, colitis might affect anti-cancer efficacy of the CTLA-4 blockade." (PMID 34203292, 2021). "In addition, if vancomycin was administered to mice with colitis and treated with anti-CTLA-4, they had more severe manifestation of intestinal disease, while administration of a common probiotic with Bifidobacterium could alleviate symptoms, without a detrimental effect on antitumour immunity." (PMID 33716996, 2021). "Colitis is the most fatal immune-related adverse event of both anti-CTLA-4 and combined anti-CTLA-4 and anti-PD-1/PD-L1 therapy." (PMID 34338882, 2021). "Overall, 1,737 colitis events were reported in the ICI group, including 1,229, 78, and 909 from anti-PD-1, anti-PD-L1, and anti-CTLA-4 drugs, respectively." (PMID 34912213, 2021). "For instance, engineering anti–CTLA-4 to selectively localize its activity at the tumor site prevented peripheral toxicity and treatment with TNF inhibitors concomitantly with CTLA-4 and PD1 antibodies ameliorated colitis while improving antitumor efficacy." (PMID 32817121, 2020). "For this purpose, we resorted to the recently described murine model of ICI-induced colitis in which a combination of DSS and anti–CTLA-4 antibody has been used." (PMID 32817121, 2020). "One SCLC patient with HBC/HCV received treatment with anti-PD-1 and anti-CTLA-4 combination ICI therapy and developed grade 2 colitis and grade 3 pneumonitis." (PMID 31847881, 2019). "Grade 3–4 irAEs are rare for PD-1 based therapies but are more common in CTLA-4 based or combination CTLA-4 plus PD-1 therapies, and are mostly commonly colitis, transaminitis, and endocrinopathies." (PMID 30631766, 2018). "In agreement, it has been shown that corticosteroid treatment leads to the up-regulation of coinhibitory molecules such as CTLA‐4, PD‐1, CD73, and FOXP3 in a colitis model." (PMID 30550561, 2018). "Pts with MM who developed select irAEs (colitis, hepatitis and arthritis) while receiving ICI (anti-PD-1, anti-CTLA-4 or combination anti-PD-1/CTLA-4) were identified." (PMID 30400835, 2018).
colitis (continued). "PD1/CTLA‐4 BsAb demonstrated significant tumor accumulation, with a 6.3‐fold increase compared to PLG‐Fc‐III‐4C‐IgG in MC38‐bearing mice, and significantly reduced the adverse colitis event related to toxicity observed with aPD1 + aCTLA‐4 in healthy mice." (PMID 39606809, 2025). "When administered with monotherapeutic checkpoint blockade, tumor‐inoculated mice treated with H11‐HLE exhibited comparable antitumor activity to those treated with anti‐CTLA‐4 antibodies, yet without the induction of colitis." (PMID 38881673, 2024). "Anti-CTLA-4 drugs inhibit CTLA-4 + Treg cells in tumors and intestines, leading to the activation of effector T cells like cytotoxic T-lymphocytes (CTLs) and resulting in ICI colitis." (PMID 39311981, 2024). "Anti‐CTLA4 nanobodies lacking the Fc domain can facilitate the response to antitumor without eliciting colitis." (PMID 39031507, 2024). "Lastly, colectomy is a rare potential treatment indicated in life-threatening colitis that has not responded to medical therapies, especially in the case of colonic perforation, which occurs mostly with anti-CTLA-4." (PMID 37511260, 2023). "There are no histological differences between anti-CTLA-4- and anti-PD-1/PD-L1-induced colitis, except for a more frequent presentation with active colitis and a higher presence of crypt atrophy in patients treated with anti-PD-1." (PMID 37511260, 2023). "In the case of CTLA-4 inhibitors colitis is more likely; in the case of PD-1/PDL1 inhibitors pneumonitis, hepatitis and neurotoxicity are more likely; and in the case of combination therapy, colitis and myocarditis are more likely." (PMID 36769093, 2023). "Although fecal microbiota transplantation (FMT) alone did not induce colitis, subsequent challenge with combination anti-CTLA4/anti-PD-1 therapy triggered increased colon mass and more marked histological changes." (PMID 37872166, 2023). "We confirm that LRBA KO mice have significantly reduced expression of CTLA4 in Treg cells but also that reduced IL17 and IL22 production by ILC3 in the gut may further exacerbate DSS-induced colitis." (PMID 35603158, 2022). "It was found that CTLA-4 inhibitor treatment in mice could lead to intestinal injuries, such as increased IEC death, imbalance of IEC and IEL homeostasis, and even colitis, and this effect was mediated by gut microbiota." (PMID 36189293, 2022). "CTLA4 expression by Treg cells and IL22 and IL17 production by ILC3 innate lymphocytes have both been shown to prevent or limit the development of inflammatory bowel syndromes and particularly colitis in the LI." (PMID 35603158, 2022). "In this study, we aimed to describe the clinical, endoscopic, and histologic characteristics of a mono-institutional cohort of patients who developed diarrhea, colitis, or other GI AEs after treatment with anti–CTLA-4 or anti–PD-1/PDL1 drugs." (PMID 35328239, 2022). "Oral administration of Bifidobacterium species rescued mice from colitis in a Treg cell dependent manner without an apparent impact on the antitumor activity of anti-CTLA-4 immunotherapy." (PMID 36713364, 2022). "In a prospective analysis of patients to be put on anti-CTLA-4 therapy, bacteroides phyla were found to be enriched in patients who did not develop colitis on checkpoint inhibitors." (PMID 35474500, 2022). "The melanoma patients treated with anti-CTLA-4 were rich in Bacteroidetes and various genetic pathways, involving polyamine transport and B vitamin synthesis, and no colitis occurred." (PMID 34568308, 2021). "Another group reported that Lrba-/- mice are susceptible to DSS-induced colitis, although this phenotype was suggested to arise from dysregulation of TLR signaling rather than impaired CTLA4 expression." (PMID 35154081, 2021).
colitis (continued). "We extracted data pertaining to the 3 CD8+ TRM cell populations and found that the CD8+ TRM cell population 2, comprised mostly cells from patients with PD-1 colitis, has markedly high expression of activation markers (HLADR, CD38) and checkpoint molecules (CTLA4, TIM3)." (PMID 34147519, 2021). "Similar to the non-adjuvant group, in the single-agent anti-CTLA4, colitis (30.8%) and hypophysitis (30.8%) were frequent treatment-related toxicities that were associated with severe, grade 3–4 adverse events in 23.1% and 15.4% of the cases, respectively." (PMID 34208218, 2021). "Colitis was the most frequent adverse event on PET/CT, observed in five patients; four of these patients received PD-1 inhibitors in combination with the anti-CTLA-4 regiment ipilimumab, which is known to often induce this reaction." (PMID 33336264, 2021). "The irAEs in the gastrointestinal (GI) tract is higher with anti-CTLA4 than with anti-PD1 therapy and increases with a combination of both and may result in diarrhea, colitis, or hepatitis." (PMID 32580338, 2020). "The abundance of Bacteroides in patients with new immune-mediated colitis treated with anti–CTLA-4 was significantly lower than that in patients without colitis treated with ipilimumab." (PMID 33488618, 2020). "Following initial treatment with anti-CTLA-4 none of the 19 AYAs developed a grade 3–4 colitis, while 71 (17.4%) of the older adults did, p = 0.046." (PMID 32726988, 2020). "When we expanded the analysis, including all anti-CTLA-4 treated patients, regardless of the treatment line, we found that only 1 of the 48 (2.1%) AYAs experienced a grade 3–4 colitis." (PMID 32726988, 2020). "Following anti-CTLA-4 treatment, no AYAs experienced a grade 3–4 colitis, while 17% of the older adults did (p = 0.046)." (PMID 32726988, 2020). "A key impediment for assessing the influence of Fc-effector function on the induction of gut inflammation in syngeneic tumor models has been the lack of measurable inflammation and colitis using surrogate anti-mouse CTLA4 antibodies." (PMID 33127658, 2020). "Although colitis is one of the most frequently reported AEs following anti-CTLA-4 treatment in large phase 3 trials, AYAs did not seem to be affected." (PMID 32726988, 2020). "None of the 19 AYAs developed a colitis following initial anti-CTLA-4 monotherapy, while 71 out of 408 older adults did." (PMID 32726988, 2020). "Altogether, these data suggest that functional blockade of CTLA4 does not exacerbate colitis per se; FcγR engagement by Fc-effector anti-CTLA4 is required to drive intestinal irAE." (PMID 33127658, 2020). "Of these, 173 (8.7%) who had developed immunotherapy-related colitis were matched with an equal number of control patients without colitis to receive immunotherapy with CTLA-4- or PD-1/PD-L1-targeted MAbs individually or in combination." (PMID 31616428, 2019). "Patients who suffer from grade 2 or higher diarrhea/colitis from CTLA-4 agents should not be rechallenged with anti-CTLA-42,4,13." (PMID 30228268, 2018). "This does not seem to be the case for anti-CTLA4 cancer therapy, as feeding Bacteroides fragilis and Burkholderia cepacia to microbiota-depleted mice decreases the extent of intestinal damage and colitis while restoring the therapeutic response to anti-CTLA4." (PMID 29719601, 2018). "Anti-CTLA-4-treated melanoma patients without colitis showed enhanced levels of Bacteroidetes as opposed to those who did develop colitis." (PMID 30158926, 2018). "We found that anti-TNF-α, antibiotics, anti-IL-12p40, anti-α4β7 integrin, CTLA4-Ig, and anti-IL-6 effectively prevented onset of colitis, whereas TNFR-Fc and cyclosporine did not." (PMID 22536543, 2012). "Using the SCID adoptive transfer colitis model, we have evaluated the effect of currently used IBD drugs and IBD drug candidates, that is, anti-TNF-α, TNFR-Fc, anti-IL-12p40, anti-IL-6, CTLA4-Ig, anti-α4β7 integrin, enrofloxacin/metronidazole, and cyclosporine." (PMID 22536543, 2012).
colitis (continued). "Enhanced colonic IL-6 was also seen in models of mice challenged with acute infection with Citrobacter rodentium or Dextran Sulfate Sodium (DSS) followed by anti-CTLA-4 administration, suggesting that IL-6 may serve as a cytokine signature in ICI-induced colitis." (PMID 39247203, 2024). "Eight out of 21 (38.1%) ICI-induced colitis patients treated with PD-1/PD-L1 inhibitor monotherapy were positive for the autoantibodies, while all five ICI-induced colitis patients treated with combination of CTLA-4 and PD-1 inhibitors were negative for the autoantibodies." (PMID 38461170, 2024). "Furthermore, spontaneous development of colitis also occurred in B7 (CD80/86) double knock-out transgenic mice due to poor stimulation of CTLA-4, with a decrease in the number of FOXP3 Treg cells also noted." (PMID 37511260, 2023). "GeoMx analysis confirmed the infiltration of colon in mice that developed colitis after transfer of toxic IgG and identified a colitis-specific gene signature with upregulation of immune cells expressing immune checkpoint inhibitors, such as LAG3, TIM-3, PD-1(PD-L1), and CTLA-4." (PMID 36058945, 2022). "By examining both systemic and tissue-specific immune changes induced by combination anti–CTLA-4 and anti–PD-1 immunotherapy, we found distinct repertoire changes in patients who developed moderate-severe colitis, irrespective of their antitumor response to therapy." (PMID 36173679, 2022). "Interestingly, both ICI targets PD-1/PD-L1 and CTLA-4 play a role in the pathophysiology of IBD, which may partially account for similarities in the immune phenotype observed between these two colitis forms." (PMID 34338882, 2021). "We observed no clear differences between CTLA-4- and PD-1-inhibitor-induced colitis samples." (PMID 34338882, 2021). "Next, we wondered whether a T cell trafficking-blocking antibody could be used to treat colitis induced by DSS with or without CTLA-4 blockade." (PMID 32183814, 2020). "Compared with no colitis patients, serum IL-17 levels were significantly higher in patients with CTLA-4-related colitis; furthermore, the growth and fall in blood IL-17 levels were, respectively, associated with the development and the resolution of colitis symptoms individually." (PMID 33123120, 2020). "Thus, in contrast to sole CTLA4 antagonism needed for combination antitumor activity Fc-effector function is required to induce immune-mediated colitis whereas CTLA4 antagonism alone is not sufficient." (PMID 33127658, 2020). "This has not been reported with Anti-CTLA4 or Anti-PD1-L1, but it is plausible that this occurs with both due to inflammation of the gut, infiltration of lymphocytes and loss of mucosa, which results in severe colitis during therapy." (PMID 32872599, 2020). "Whether or not the reduced IL-10 production by Bcl-3-overexpressing Tregs is the sole reason for the colitis is not clear, as we also noticed decreased expression levels of Foxp3, CTLA-4, GITR and IL-2R in these Treg cells." (PMID 28452361, 2017). "Neither patient had evidence of CTLA-4 antibody-related colitis prior to starting HD IL-2 therapy." (PMID 27660706, 2016). "Patients who did not develop gastrointestinal inflammation following CTLA-4 blockade are herein referred to as colitis free (C-F) and patients who experienced inflammatory complications after CTLA-4 blockade are referred to as having progressed to colitis (PtC)." (PMID 26837003, 2016). "Colitis is more commonly seen with anti–CTLA-4 agents and may be seen without diarrhea." (PMID 29282426, 2016). "Indeed, the Powrie group demonstrated that while suppression of colitis by wild type Treg cells was CTLA-4 dependent, CTLA-4−/− Treg cells were able to use IL-10 to elicit suppression, providing a precedent for the compensation of CTLA-4 function by the IL-10 pathway." (PMID 26596798, 2015).